NOTCH2 (notch receptor 2)
Diseases named in the same sentence as NOTCH2 in open-access papers (continued):
Sharing a sentence is not in itself a finding about the gene and the disease.
cancer (continued). "For instance, genes like NOTCH2, IFNGR2, and MDM2 are upregulated in the Pathways in Cancer—specifically, NOTCH2 and IFNGR2." (PMID 40621499, 2025). "For many targets like CLMP, PDGFRB, NOTCH2, and GPC6, TCGA SARC samples had the highest median expression compared with other cancer types in the TCGA Pan-Cancer Atlas." (PMID 40814001, 2025). "Notch pathway negatively impacts the activity of the Wnt pathway in most cancers; Wnt can also impact the expression of DLL1, HES1 and NOTCH2 on the protein level, while β-catenin can also interact with NOTCH1 and reduce its ubiquitination." (PMID 40002854, 2025). "Stabilized Notch2 activates downstream signaling components such as C-Myc, Cyclin D3, and HES1, which drive cancer cell survival and chemoresistance." (PMID 40393971, 2025). "Our most important finding is a possible involvement of Notch-2 and its signalling pathway (dynamin-2, nicastrin, SPARC and PROS1) in dormancy of cancer spheroids in a HMW-HA concentration (5 wt%) representative of normal brain ECM." (PMID 40881990, 2025). "Based on our data, activated forms of Notch1, Notch2, Notch3, and Notch4 (N1ICD, N2ICD, N3ICD, and N4ICD) in stomach-cancer cells were all upregulated, especially N1ICD and N2ICD, after the co-culture of cancer cells and macrophages." (PMID 35382168, 2022). "Subcluster 3 expressed limited epithelial marker of EPCAM but cancer stem cell marker CD44 and NOTCH2." (PMID 35733218, 2022). "The genomic profiling of GC PNM also identified alterations in other cancer-related genes, including NOTCH1, NOTCH2, NF1, and STK11." (PMID 35515115, 2022). "Indeed, previous studies by us and others have shown that PINCH-1 can interact with multiple signaling proteins including ILK 37, Nck-2 60, RSU-1 61, 62, EPLIN 50, myoferlin 53 and Notch-2 55, which may also contribute to the regulation of cancer cell proliferation and survival." (PMID 35401828, 2022). "Three clinically significant and highly studied genes were selected as target genes for each cancer type: HERE2, MYBL2, and MMP11 for BRCA and NOTCH2, BRCA1, and PDC for COAD." (PMID 34422018, 2021). "According to the published data, GINS1, p21, GLP-1, Notch2, and FZD-1 play important roles in the stemness of cancer stem cells." (PMID 31375149, 2019). "Cytoscape analysis of gene network revealed important cancer pathways including hub genes at NFGR, MAPK3, and SMAD7 for OS, and hub genes at FOXP1, MAP2K5, FGFR1, and NOTCH2 for DFS." (PMID 31608231, 2019). "We found that NOTCH2, KAT6A and RALGPS2 are all potential cancer driver genes, demonstrating that this method can help us to find RNA structure-related cancer driver elements." (PMID 31160636, 2019). "The Notch2 and FZD-1 proteins, important members of the Notch and Wnt signaling pathways, respectively, in cancer stem cells, play important roles in the proliferation and stemness maintenance of cancer stem cells." (PMID 31375149, 2019). "In this case, the 5′UTRs of KAT6A and NOTCH2 were identified at a q-value cutoff of 0.05, and both genes were discovered in the CGC, and are regarded as known cancer genes." (PMID 31160636, 2019). "Ectopic miR-181b expression suppressed cancer stem cell properties and enhanced the sensitivity to DDP treatment by directly targeting Notch2." (PMID 30470250, 2018).
cancer (continued). "Cancer stem cell (CSC)-like properties were tested by a cell proliferation assay and flow cytometry; miR-181b expression was measured by real-time PCR; and Notch2 and related proteins were detected by Western blotting and immunohistochemistry." (PMID 30470250, 2018). "In this study, we found that ectopic miR-181b expression suppressed cancer stem cell properties and enhanced sensitivity to cisplatin (DDP) treatment by directly targeting Notch2." (PMID 30470250, 2018). "Signal transduction genes (i.e., ADCY4/7/8/9,) are also in the list of our 102 genes, which also includes cancer stem cell signaling genes (i.e., WNT7A, GLI1/2/3, NOTCH2/3/4, ALDH1A3)." (PMID 29304754, 2018). "Collectively, we present converging evidence from our studies that Notch2 is a critical mediator of radiation-induced EMT and responsible for induced malignant tumor growth." (PMID 27462787, 2016). "Since miR-34a suppresses many oncogenes and cancer stem cell markers including CD44, CDK4, CDK6, c-Met, Notch-1, Notch-2, SIRT1 and DLL1 as its target genes, miR-34a plays important roles in cancer stem cells." (PMID 26580663, 2015). "Across the cancer tissues, expression of HES1 mRNA was significantly increased compared to normal bladder, despite the significant downregulation of NOTCH1, NOTCH2 and DLL1." (PMID 25167871, 2014). "Because apoptosis induction is considered an important mechanism in cancer chemoprevention by SFN, it was of interest to determine the consequences of Notch2 activation on proapoptotic response to SFN." (PMID 22970326, 2012). "In our cancer sample, we detected that the first intron of PTGFRN is fused with the 3′ junction of the 17th exon of NOTCH2 to generate a chimeric PTGFRN-NOTCH2 transcript." (PMID 22905095, 2012). "The “Pathways in Cancer” involve ITGB1, NOTCH2, and HSP90AB1 genes." (PMID 40621499, 2025). "Additionally, BIN1 regulated cancer stem cell properties through modulation of ALDH1 expression, with NOTCH2 acting as a crucial downstream mediator of ALDH1 signaling." (PMID 40016843, 2025). "The aberrant activity of CDK6, NOTCH2, and FGFR2 is described and often associated with more aggressive disease phenotypes in certain types of cancer, but it has not yet been studied in SLCT." (PMID 39592485, 2025). "NOD2-induced nonclassical monocytes are believed to develop in the absence of Notch2 signaling and mediate protection against cancer metastases." (PMID 41244563, 2025). "Additionally, MDK triggers NOTCH1 and NOTCH2 signaling, pathways known to promote EMT and chemoresistance in multiple cancer types." (PMID 40500394, 2025). "NOTCH2 and NOTCH4 are well-known genes in BRCA and other cancers." (PMID 38977697, 2024). "While CAFs-S1 stimulate cancer cell migration and initiate an EMT through CXCL12 and TGFB pathways, highly contractile CAFs-S4 induce cancer cell invasion in 3 dimensions via NOTCH signaling (NOTCH1, bSE = 3.0; NOTCH2, bSE = 2.6; NOTCH3, bSE = 1.4; NOTCH4, SE = 3.0)." (PMID 39335478, 2024). "In addition, cluster 4 and 1 expressed cancer stem cell-like cells (CSCLCs) gene markers CD24, CD44, and EPCAM, whereas cluster 0 and 2 expressed CD44 and NOTCH2, a gene marker denoted the activation of CSCLCs." (PMID 35733218, 2022). "MDK has been reported to promote cancer EMT via TGF-β, WNT and Notch 2 signalings." (PMID 35747815, 2022). "Despite previous studies on roles of Notch2 in skeletal development and diseases, there is a lack of knowledge about the potential roles of Notch2 signalling in cancer chemotherapy-induced bone defects." (PMID 35563828, 2022). "Other cancer amplified genes that also significantly increase ARE reporter activity are MYC (a previously known gene to exert post-transcriptional effect), MYCN, CCND1, CCNE1, SKP2, and NOTCH2." (PMID 34535639, 2021). "The CTLs are involved in cancer immunosurveillance, and Notch 2, unlike Notch 1, seems to be required for the efficient induction of their antitumoral activity." (PMID 33374160, 2020).
cancer (continued). "In addition, MDK secreted from NSCLC cells interacted with Notch2 which activated the Notch signaling pathway and induced EMT, upregulated NF-κB, and increased cancer promotion." (PMID 32847073, 2020). "In this context, the transcription factor YB-1 could promote cancer stem cell proliferation, maintain cancer stem cell stemness, and suppress cancer stem cell apoptosis by promoting the expression of GINS1, p21, GLP-1, Notch2, and FZD-1." (PMID 31375149, 2019). "In the present study, the results revealed that the transcription factor YB-1 could maintain the stemness of cancer stem cells by promoting the expression of stemness-related genes (FZD-1, p21, GLP-1, GINS1, and Notch2)." (PMID 31375149, 2019). "In this study, DAPT inhibited cancer growth both in vitro and in vivo, but Notch2/DLL rather than Notch1/Hes1 signaling was responsible for those effects in GH3 cells." (PMID 31508369, 2019). "In addition to Nanog, other stemness genes including Notch2, CTNNB1 and Hsp90B1 are also important to CSCs and cancer cells." (PMID 27917123, 2016). "In this study, we detected a cancer-restricted gene fusion between PTGFRN and NOTCH2 in CRC." (PMID 22905095, 2012). "Furthermore, bioinformatic analysis of miR‐34a targets in various cancers identifies numerous target genes such as Jagged 1 (JAG1), CD44, SRY (sex determining region Y)‐box 4 (SOX4), Notch homolog 2 (NOTCH2), Matrix metallopeptidase 9 (MMP9), Interleukin 6 (IL‐6), and SMAD family member 4 (SMAD4)." (PMID 40336533, 2025). "Furthermore, our data do not prove that NOTCH2 P2113S is differentially expressed in different stages and histological types of human OC tissues, nor does it verify its ability to promote cancer progression in different OC cell lines." (PMID 37728427, 2023). "Since many studies have proved the oncogenic effect of Notch1 and Notch2, we collected the supernatant from the co-culture as the cell-culture-conditioned medium and measured cell proliferation using MTT assay to verify the effect of co-culture on the proliferation of cancer cells." (PMID 35382168, 2022). "In summary, macrophages could induce the activation of DLL3-dependent Notch1/Notch2 signaling, the upregulation of IL-33, and the degradation LG3BP and HSPA8, resulting in enhanced cancer-cell proliferation and elevated IL-1β, IL-12, and IL-10 secretion by macrophages." (PMID 35382168, 2022). "Several studies have been conducted on NOTCH2 and cancer, not all in accordance with our results." (PMID 31159827, 2019). "Combining our results and previous reports, it could be concluded that the transcription factor YB-1 promotes cancer stem cell proliferation, maintains cancer stem cell stemness, and suppresses cancer stem cell apoptosis by promoting the expression of GINS1, p21, GLP-1, Notch2, and FZD-1." (PMID 31375149, 2019). "Also, HLA-A, MED1, NOTCH2 and NOTCH3 are related with cancer prognosis." (PMID 30545040, 2018). "ASCL1 KO tumors developed a poorly differentiated carcinoma without detectable expression of the NE lineage markers SYP, INSM1, or DLL3 but showed higher expression of NOTCH2, HES1, and KRT8." (PMID 39024561, 2024). "NOTCH2/3 and DLL4 can significantly differentiate non-cancerous samples from cancers and were broadly altered in subgroups." (PMID 34205690, 2021). "Present data show that NILCO molecules (Notch1, Notch2, Notch3, Notch4, DLL4, and JAG1) and targets (Survivin, Hey2, IL-1R tI, and OB-R) were expressed in EmCa regardless of ethnicity and cancer type." (PMID 28659656, 2017). "We also examined the expression of other Notch receptors (Notch2, Notch3, and Notch4) in ICC tissue and noncancerous tissue adjacent to the cancer lesions." (PMID 23688168, 2013).
infection (16 papers, 2012 to 2026). The state of being infected such as from the introduction of a foreign agent such as serum, vaccine, antigenic substance or organism. "Notch1 and Notch2 inactivation in T cells conferred susceptibility to infection, but mice with a similar conditional loss of RBP-Jκ remained protected." (PMID 31690218, 2019). "In other infection models, Notch2 loss impaired CD8+ T cell function and conferred susceptibility to the parasite Trypanosoma cruzi." (PMID 31690218, 2019). "Infection with Ad-CMV-Cre resulted in the deletion of Rbpj and the loss of the stimulatory effect of the NOTCH2 gain-of-function on the Notch target genes Hes1, Hey1, and Hey2 (not shown) since RBPJκ is required for their induction by Notch." (PMID 37865314, 2023). "We also observed that Notch-2 ligation inhibited the very low levels of BZLF1 transcription that occur during in vitro infection of primary B cells." (PMID 25122803, 2014). "Western blotting was used to detect whether Notch2 protein was overexpressed in NPC cells after infection." (PMID 34224316, 2021). "One such cue, Notch-2, may be particularly relevant to the biology of infection with Epstein-Barr virus (EBV), which colonizes the B cell compartment." (PMID 25122803, 2014). "Notably, the expression of Notch2 decreased throughout the course of infection." (PMID 28676722, 2017). "SARS-CoV-2 infection resulted in a significant overexpression of Notch1, Notch2, CTNNB1, CDC42, and PSEN1 after 24 h of infection." (PMID 37211584, 2023). "Treatment with 2-pyridone PIM1 inhibitor was able to significantly downregulate Notch1, Notch2, CTNNB1, and CDC42 in SARS-CoV-2-infected cells at 24 h post-infection (p-value < 0.001)." (PMID 37211584, 2023). "We overexpressed the intracellular domains of the Notch2 (NICD2) and Notch3 (NICD3) by lentiviral infection of human aortic smooth muscle cells and examined gene expression by qPCR." (PMID 22615991, 2012). "No Notch2+ Inf DCs/MΦs were observed since there was no monocyte differentiation in lungs before infection." (PMID 35603470, 2022). "hTERT transactivates the NOTCH2 promoter via NF-κB signaling while EBNA2 mimics NOTCH2 signaling and induces BATF expression early after infection of primary B-cells, which may play a key role in the establishment of latency." (PMID 28792435, 2017). "By contrast, infection of LCLs with retroviral vectors expressing functional NOTCH2 did not alter TERT transcript levels." (PMID 26018735, 2015). "Here, mice carrying a T cell specific deletion of Notch1 (N1ΔCD4Cre), Notch2 (N2ΔCD4Cre) or both Notch1 and Notch2 (N1N2ΔCD4Cre) on a resistant C57BL/6 genetic background were infected with L. major to study the importance of Notch receptors in Th1 differentiation and resolution of the infection." (PMID 22396647, 2012). "However, some genes, such as Jak2, Notch2, and Runx1, were up-regulated in KRAS+ mice regardless of infection status." (PMID 33310760, 2021).
genetic disorder (10 papers, 2017 to 2024). "ALGS is a rare genetic disorder characterized by liver, heart, eye, and skeletal abnormalities due to mutations in JAG1 or NOTCH2 genes." (PMID 39175640, 2024).
kidney disease (7 papers, 2018 to 2025). "The two causative genes JAG1 and NOTCH2 are expressed during kidney development, can be reactivated during adulthood kidney disease, and Notch signalling is essential for vascular morphogenesis and remodelling in mice." (PMID 39446153, 2025). "Notably, FOXN2 had genetic variants statistically associated with the risk of both AD and SCZ, and NOTCH2 displayed genetic variants that are statistically associated with the risk of both endocrine disease and kidney disease." (PMID 36204511, 2022).
cardiac diseases (3 papers, 2022 to 2025). "In addition, NOTCH2 mutations resulted in multiple cardiac diseases and vascular anomalies." (PMID 36338034, 2022). "The finding that the aberrant expression of miR-29b-3p could influence cardiac development via NOTCH2 highlights the role of epigenetic factors in the development of heart disease." (PMID 37189655, 2023).
female genital system diseases (2 papers, 2019 to 2023). "It was also reported that NOTCH2 was associated with OC and female genital system diseases, indicating that NOTCH2 plays a role in OC development." (PMID 37728427, 2023).
hematologic malignancies (2 papers, 2017 to 2018). "For example, NOTCH2 was reported to promote cell proliferation in T-ALL cell lines;30 the stably upregulated REL as a TF could decrease cell apoptosis of hematologic malignancies." (PMID 30195757, 2018).
gynecologic tumors (1 paper, 2025). "Notch receptor NOTCH2 and Wnt gene CTNNB1 expression were also significantly reduced in other gynecologic tumors when compared to benign tissues (FC = 1.32, and 1.62, respectively; p = 0.002)." (PMID 40002854, 2025).
neurodegenerative disease (1 paper, 2024). A disorder of the central nervous system characterized by gradual and progressive loss of neural tissue and neurologic function. "More specifically, 1, 1, 312, and 4 mutations in Notch1, Notch2, Notch3, and Notch4, respectively, were identified to be correlated with neurodegenerative diseases." (PMID 38790158, 2024).
neurological disorders (1 paper, 2022). "Several of these such as NOTCH2, APP, ITM2B and PTGDS have been implicated in neurological disorders." (PMID 36185601, 2022).
skeletal disease (1 paper, 2025). "In a murine model of Notch2-related skeletal disease, an antibody against the Negative Regulatory Region of Notch2 reversed OP." (PMID 41221409, 2025).
vascular disorder (1 paper, 2019). A general term used to describe any disease affecting blood vessels]. "Among the identified genes in this study, several genes including MTHFR, NOS3, SLC44A2, and NOTCH2 are associated with prothrombotic risk factors and various vascular disorders." (PMID 32038468, 2019).
NOTCH2 also shares sentences with these, for which no sentence is quoted: esophageal squamous cell carcinoma (4 papers); pancreas carcinoma (4); autosomal dominant disease (3); Obesity (3); pancreatic ductal adenocarcinoma (3); acute T-cell lymphocytic leukemia (2); Alagille syndrome type 1 (2); astrocytoma (2); cardiovascular disease (2); desmoid tumor (2); infectious disease (2); lung squamous cell carcinoma (2); Lymphocytic Leukemia (2); multiple myeloma (2); myeloid leukemia (2); Myocardial fibrosis (2); non-alcoholic fatty liver disease (2); periodontal disease (2); premature ovarian failure (2); adenocarcinoma (1); adenovirus infection (1); Airway obstruction (1); Alzheimer disease (1); amyloid (1); Anxiety (1); arteriopathy (1); autosomal recessive spondylocostal dysostosis (1); basal cell carcinoma (1); cardiac ischemia (1); chronic GVHD (1).
A further 92 diseases each share a sentence with NOTCH2 in 1 paper.